HIF1A (hypoxia inducible factor 1 subunit alpha)
Diseases named in the same sentence as HIF1A in open-access papers (continued):
Sharing a sentence is not in itself a finding about the gene and the disease.
breast cancer (continued). "Recently, Finley further found that SIRT3 could mediate metabolic reprogramming in human breast cancer cells by destabilizing HIF1α." (PMID 25103363, 2014). "In addition, P2Y2R activation by ATP in breast cancer cells induces HIF-1α expression, LOX secretion, and collagen crosslinking, which forms a receptive microenvironment for pre-metastatic niche formation." (PMID 25238333, 2014). "Moreover, high HIF-1α levels were shown to be predictive of response to epirubicin therapy in patients with breast cancer." (PMID 25128202, 2014). "Additionally, when we tested the ability of another highly metastatic breast cancer cell SK-BR-3 to induce HIF-1α expression and LOX release, SK-BR-3 dramatically induced HIF-1α expression and LOX release by hypoxia." (PMID 25238333, 2014). "The expression of unhydroxylated HIF-1α positively correlates with VHL in breast cancer suggesting that VHL may be rate-limiting for HIF degradation." (PMID 24563687, 2014). "Thus, we treated SUM149 breast cancer cells with CoCl2 in order to increase the expression of HIF-1α." (PMID 25269858, 2014). "That our experimental conditions could successfully elicit hypoxic stress in breast cancer cells was separately verified by assessing the expression profile of HIF1α, an established cellular biomarker of hypoxia." (PMID 25051364, 2014). "In addition to T47D cells, LXY6006 also blocked hypoxia-induced HIF-1α accumulation in other tested breast cancer cells." (PMID 24925080, 2014). "Additional studies showed that +SA mammary tumors grown in syngeneic mice also displayed elevated HIF-1a levels and enhanced Akt/mTOR, p70S6K, and eIF-4E1 activation, and treatment with compound 44, but not its parent compound, δ-tocotrienol, blocked this compensatory response to hypoxic conditions." (PMID 25140303, 2014). "In addition, human breast cancers with high HIF-1α and OGT levels, and low OGA levels are correlated with poor patient outcome." (PMID 25426101, 2014). "We undertook the present study to test the hypothesis that oxygen-CNTs inhibit breast cancer cell proliferation induced by HIF1α." (PMID 25089613, 2014). "Staining for hydroxylated HIF-1α can identify a subset of breast cancer patients with poorer prognosis and may be a better marker than total HIF-1α levels." (PMID 24563687, 2014). "The nuclear staining of HIF-1α was positive in 53% (81/153) of breast cancers." (PMID 23326384, 2013). "Molecular mechanisms study demonstrated that ISL could significantly inhibit VEGF expression in breast cancer cells via promoting HIF-1α (Hypoxia inducible factor-1α) proteasome degradation and directly interacted with VEGFR-2 to block its kinase activity." (PMID 23861918, 2013). "The results showed that in MDA-MB-231 breast cancer cells, the HIF-1α degradation speed was much faster in the ISL treated group than that in the control group, indicating that the proteasome degradation pathway might be activated." (PMID 23861918, 2013). "This study is the first to identify HIF-1α as a modulator of PII-driven aromatase expression in human breast tumor-associated stroma and provides a novel mechanism for estrogen regulation in obesity-related, post-menopausal breast cancer." (PMID 23566437, 2013). "Interestingly, we have identified a novel non-HIF-1α-mediated response to hypoxia in breast cancer cells and high-grade or recurrent breast tumors." (PMID 24860738, 2013). "PTEN loss and expression of c-Kit, c-Met, HIF-1α, PDGFRA VEGFR2, and VEGF-A have been reported to be worse prognostic factors for breast cancer, whereas expression of IGF-1R, Bcl-2 and survivin are reportedly good prognostic factors for breast cancer." (PMID 24245483, 2013).
breast cancer (continued). "Interestingly, the S. triloba inhibited the expression of VEGF at the mRNA and protein and the HIF-1α mRNA in the MCF 7 breast cancer cells under both normoxic and hypoxic conditions." (PMID 24330494, 2013). "Here, we investigated the effect of hypoxia on the expression of NMB-R and determined whether HIF-1α directly influences hypoxic induction of NMB-R in MDA-MB-231 breast cancer cells." (PMID 24349381, 2013). "Moreover, to test the extracts’ indirect antiangiogenic activity, the effect on the expression of the VEGF protein and expression of both, VEGF and HIF-1α mRNA was examined using MCF 7 breast cancer cell line." (PMID 24330494, 2013). "Considering the crucial interplay between cancer cells and stroma, the HIF-1α/GPER transduction pathway may be pointed out as a further biological target towards innovative treatments in breast cancer." (PMID 23947803, 2013). "Recent evidence suggests that increased release of exosomes from breast cancer cells under hypoxic condition may be mediated by transcriptional factor HIF-1α." (PMID 23861904, 2013). "Moreover, we show that upregulation of NMB-R by hypoxia is mediated by HIF-1α-dependent transcriptional activity in breast cancer cells." (PMID 24349381, 2013). "The results showed that in both breast cancer cells, the HIF-1α degradation speed was much faster in the EGC treated group than that in the control groups, indicating that the proteasome degradation pathway might be activated." (PMID 23457597, 2013). "To demonstrate whether HIF-1α is associated with NMB-R expression in human neoplastic breast tissues, we performed immunohistochemical double-staining using a breast cancer tissue array." (PMID 24349381, 2013). "In addition, DDX3 was shown to be a direct downstream target of HIF-1α (the master regulatory of the hypoxia response) in breast cancer cell lines." (PMID 23696831, 2013). "In non-BRCA mutation-related breast cancer, HIF-1α overexpression plays a role in carcinogenesis and correlates with poor prognosis." (PMID 23409121, 2013). "We hypothesized that HSE could suppress phosphorylation of STAT5 and STAT3, and the expression or release of IGF-1R, VEGF, VEGF-R2 and HIF-1α proteins in human breast cancer xenografts in vivo." (PMID 22792362, 2012). "To verify whether estrogen was able to induce HIF-1α in breast cancer cells in vitro, we treated the estrogen receptor positive TG1-1 cells with E2 and observed an induction of HIF-1α in nuclear lysates at approximately 24 hours." (PMID 23088607, 2012). "Breast cancer is the most common cancer among women and is studied as an angiogenic carcinoma due to the high expression levels of proangiogenic factors, such as VEGFs, HIF-1α, TGF-β, or thymidine phosphorylase (TP), in carcinoma cells." (PMID 22007214, 2012). "Recent whole-genome expression profiling of breast cancers has revealed that the hypoxic response (predominantly through HIF-1α), the EGFR and signal transducer and activator of transcription 3 (STAT3) pathways are positively correlated together in TNBCs as compared to luminal cancers." (PMID 22225988, 2012). "EZH2 expression may also be triggered by hypoxia, a condition present in nearly all solid tumors: HIF1α-dependent transactivation of EZH2 was demonstrated in breast cancer-initiating cells." (PMID 23110793, 2012). "In stark contrast to results obtained previously, we found that HIF-1α plays a significant role in the control of primary PyMT-induced mammary tumor growth under either standard (50,000-cell input) or limiting dilution cell transplantation conditions (50- to 500-cell input)." (PMID 22225988, 2012). "Moreover, the specific contribution of HIF-1α in regulating TICs in breast cancer remains undefined, particularly in the context of syngeneic rodent models that recapitulate the breast cancer microenvironment." (PMID 22225988, 2012). "RON tyrosine kinase is a direct target of HIF-1α and mediates invasion of breast carcinoma cells." (PMID 23241400, 2012).
breast cancer (continued). "We wished to examine whether Rac1 influences HIF-1α expression in breast cancer cells under hypoxia." (PMID 21980400, 2011). "In this study, we have demonstrated that basal-like breast cancers have an intrinsically elevated SIAH2 level as part of its phenotype that may, partly at least, explain the mechanism underlying high HIF-1α expression in this tumor subtype." (PMID 21306611, 2011). "Therefore, to understand the process responsible for HIF-1α accumulation in response to E2 treatment, the effect of E2 on HIF-1α mRNA expression in breast cancer lines was investigated." (PMID 21897387, 2011). "We have recently shown that VEGF and HIF-1α, as well as phosphorylated Akt, are expressed in CTCs of most metastatic breast cancer patients; therefore, it was interesting to further investigate the expression of Twist in CTCs of breast cancer patients." (PMID 21663619, 2011). "It is possible that these proteins affect HIF-1α expression in hypoxic breast cancer cells." (PMID 21980400, 2011). "Therefore, hypoxia directly induces the expression and activation of HIF-1α in breast cancer cells, which is a critical step in tumor angiogenesis." (PMID 21980400, 2011). "DDX3 and HIF-1α are highly expressed in the very aggressive breast cancer cell line, MDA-MB-231." (PMID 21448281, 2011). "Interestingly, HIF1 promoter activity was observed to be significantly increased in the breast cancer cells consistent with HIF-1α level on E2 stimuli." (PMID 21897387, 2011). "Several matching profiles (Results 2, 3, 5 and 9) implicate FoxO3 in hypoxia response: data from GDS2758 and GDS2760 compare MCF-7 breast cancer cells under hypoxic and normoxic conditions as well as with siRNAs targeting hypoxia-inducible factor 1 (HIF-1α) and HIF-2α." (PMID 21172034, 2010). "The authors describe the presence of different HIF-1α splice variants in human breast cancer and non-malignant tissue samples." (PMID 20624302, 2010). "The aim of our study was to analyze the relationships between hypoxia markers HIF-1α, Glut-1, leptin, leptin receptor (ObR) and other breast cancer biomarkers in primary and metastatic breast cancer in patients treated or untreated with preoperative chemotherapy." (PMID 20569445, 2010). "The prognostic relevance of HIF-1α protein overexpression has been shown in breast cancer." (PMID 20624301, 2010). "Similarly, activation of PPAR-γ induced autophagy in breast cancer cells through upregulation of the HIF-1α protein and BNIP3." (PMID 21179212, 2010). "In breast cancer, we showed that patients with a diffuse (non-hypoxia associated) HIF-1α staining pattern had a relatively better prognosis." (PMID 20565904, 2010). "HIF-1α knockdown in breast carcinoma MCF-7 cells was shown to elevate the sensitivity to chemotherapeutic agent methotrexate and resistance induced by hypoxia against doxorubicin and cisplatin in non-small cell lung cancer was reversed by silencing HIF-1α protein." (PMID 20626868, 2010). "Previous studies have found that down-regulation of HIF-1α could significantly decrease the levels of survivin expression in BxPc-3 pancreatic cancer cells and breast cancer cells." (PMID 19245702, 2009). "Since FAK is implicated in the angiogenesis process and induces the expression of VEGF, it was of interest to evaluate whether CTCs from breast cancer patients have activated the angiogenesis pathway by expressing HIF-1α and VEGF." (PMID 19919679, 2009). "Overexpression of HIF-1α has been previously reported to correlate with angiogenesis, an aggressive phenotype and poor outcome after conventional adjuvant therapy in breast cancer." (PMID 19778456, 2009). "We showed that 2ME2 decreases HIF-1α protein expression in MDA-MB-231 breast cancer cells in vitro." (PMID 19727403, 2009).
breast cancer (continued). "Double staining experiments revealed that HIF-1α was expressed in 76% of breast cancer patients and this expression was observed both in the cytoplasm and the nucleus although, in general, cytospin preparations are not the optimal material to study the intracellular distribution of molecules." (PMID 19919679, 2009). "The exact mechanism for the inverse association between the HIF-1α 1790 G/A polymorphism and breast cancer was not clear." (PMID 20035632, 2009). "In breast cancer cell lines LY294002 inhibited HIF-1α induction and phosphorylation under hypoxia." (PMID 19384426, 2007). "Nevertheless, even HIF-1α immunohistochemistry on TMAs has provided relevant data in breast cancer." (PMID 16035955, 2005). "Furthermore, it might hasten the malignant growth of tumors and enhance the stem cell properties and the EMT-like characteristics of breast cancer cells by increasing HIF-1α expression." (PMID 41614928, 2026). "Consequently, HIF-1α is a key target in breast cancer treatment, and such inhibitors of HIF-1α may prove to be a viable treatment option." (PMID 41614951, 2026). "Finally, we conducted knockout experiments targeting the HIF-1α, ATF4 and the programmed cell death 6 interacting protein (PDCD6IP) gene, which encodes the Alix protein, to investigate their roles in tramadol-induced cell death in breast cancer cells." (PMID 41526224, 2026). "In addition, by encouraging the breakdown of hypoxia-inducible factor 1α(HIF-1α) protein and preventing the stimulation of the PI-3 K/Akt/mTOR/HIF-1α/VEGF axis, dauricine reduces the creation of HIF-1α protein, which in turn prevents angiogenesis in human breast cancer cell lines." (PMID 40205002, 2025). "In addition, correlational studies involving patients with breast cancer revealed an association of PGK1 with paclitaxel resistance and cell survival factors, such as HIF-1α and immune checkpoints, although these need to be further investigated in future studies." (PMID 40214422, 2025). "Additionally, we explored whether the observed upregulation of the VEGF gene induced by ERRα in endothelial cells and breast cancer cells could also be mediated by HIF-1α." (PMID 40723264, 2025). "Moreover, HIF1α promotes breast cancer progression by modulating the TGFβ1/SMAD3 axis." (PMID 38361941, 2024). "Thus, hypoxia regulates CD44 expression via HIF-1α in breast cancer and gastric cancer." (PMID 38247821, 2024). "Finally, public breast cancer database analyses demonstrated that ITGB4 correlates with PTPRZ1 and that high expression of ITGB4, UCHL1, HIF1A, and PTPRZ1 associated with decreased overall survival, distant metastasis free survival, post progression survival, and relapse-free survival." (PMID 39518121, 2024). "Indeed, tumor-associated macrophages (TAMs) secrete EVs-containing lncRNA HIF-1α-stabilizing long non-coding RNA (HISLA) and potentiate aerobic glycolysis and resistance to apoptosis in recipient breast cancer cells by blocking the interaction of PHD2 and HIF-1α, thereby stabilizing HIF-1α." (PMID 39585046, 2024). "Furthermore, berberine-derived silver nanoparticles induce apoptosis in breast cancer cells by suppressing the expression of HIF-1α through the inhibition of the expression of the PI3K/AKT and Ras/Ras/ERK protein in signaling pathways and the generation of reactive oxygen species (ROS)." (PMID 38334679, 2024). "Breast cancer cells and prostate cancer cells exposed to hypoxia in vitro had reduced levels of topoisomerase IIα, a DNA binding protein essential for DNA-damaging agents to introduce double strand breaks, and such decrease was reversed by the knockdown of HIF-1α." (PMID 38730681, 2024). "Moreover, NRF2 promotes the malignancy of breast cancer through its interaction with HIF‐1α." (PMID 38140764, 2024).
breast cancer (continued). "Thus, we made a novel observation that ERα transcriptionally activates UBE2M through HIF-1α, suggesting that overexpression of UBE2M may be attributed to the high expression of HIF-1α in ER+ breast cancer." (PMID 39138151, 2024). "Furthermore, it was found that adipocyte-derived EVs could enhance the growth, motility, and invasion of breast cancer cells by stimulating the activity of HIF-1α in tumor cells." (PMID 39697630, 2024). "Luteolin- and silibinin-co-loaded with SDPN alleviated breast cancer metastasis in 4T1 tumor-bearing mice by regulating the conversion of tumor-associated M2 macrophages into the M1 phenotype and reducing the proportion of the M2-phenotype through co-action on STAT3 and HIF-1α." (PMID 37403048, 2023). "HIF-1α-stabilizing long noncoding RNA (HISLA) was demonstrated to be transmitted from tumor-associated macrophages (TAMs) to breast cancer cells via secreted exosomes causing metabolic reprogramming by enhancing aerobic glycolysis and apoptosis resistance of breast cancer cells." (PMID 36979019, 2023). "In addition, the Notch signaling pathway is activated by HIF-1α, which could promote CSC-associated tumor metastasis in lung cancer, ovarian cancer and breast cancer." (PMID 37853437, 2023). "However, the same study showed that HIF-1α inhibition could decrease chemoresistance in diabetic breast cancer patients, the used inhibitor was PX-478 which presented only some specificity to the HIF-1α isoform." (PMID 36139678, 2022). "Since it has been reported that NANOG expression is controlled by Hif-1α and that they cooperate, promoting self-renewal in breast cancer stem cells, we therefore hypothesize that the GBM subgroup with HIF1A-KDM5C hyperactivity has a distinctive stemness expression signature." (PMID 36142158, 2022). "Collectively, these results illustrated that hypoxia-responsive long noncoding NDRG1-OT1 could be transcriptionally activated by HIF-1α, act as a miRNA sponge of miR-875-3p, translate a small peptide (66 a.a.), and promote tumor growth and migration in breast cancer cells." (PMID 36127332, 2022). "To conclude, in the present study, we identified the pregnane alkaloid derivative 1 as an HSP90α inhibitor that could suppress breast cancer metastasis and angiogenesis by modulating the HIF-1α/VEGF/VEGFR2 pathway and the phosphorylation of downstream signaling molecules in vitro and in vivo." (PMID 36296726, 2022). "Therefore, this study used breast cancer as the research object to explore whether HNK can also affect the glucose metabolism of breast cancer cells through HIF-1α and its possible regulatory mechanism." (PMID 35350760, 2022). "Thus, CD47 expression is fatal for breast cancer phenotype that is mediated by HIF-1α." (PMID 36014432, 2022). "Moreover, circRNF20 (hsa_circ_0087784), circulated from RNF20 gene exon-3 to exon-5, has been newly identified in breast cancer samples, and promotes the progress and glycolysis of breast cancer by abrogating the miR-487a-mediatied inhibition of the HIF-1α/HK2 axis." (PMID 35915091, 2022). "Moreover, knockdown of HIF-1α suppressed HCG18 expression in breast cancer cells." (PMID 36139678, 2022). "Our work identified that the abnormal YTHDF1 in breast cancer cells was driven by the hypoxic microenvironment, which could induce the expression of HIF1α while inhibiting endogenous miR-16-5p, of which the latter could interact with 3′UTR of YTHDF1 mRNA to inhibit YTHDF1 expression." (PMID 35319018, 2022). "Moreover, HIF-1α activates the transcription of CD47 in breast cancer cells in hypoxia." (PMID 35565420, 2022).